SLC25A5 (solute carrier family 25 member 5)
Description:
ADP:ATP antiporter that mediates import of ADP into the mitochondrial matrix for ATP synthesis, and export of ATP out to fuel the cell (By similarity). Cycles between the cytoplasmic-open state (c-state) and the matrix-open state (m-state): operates by the alternating access mechanism with a single substrate-binding site intermittently exposed to either the cytosolic (c-state) or matrix (m-state) side of the inner mitochondrial membrane (By similarity). In addition to its ADP:ATP antiporter activity, also involved in mitochondrial uncoupling and mitochondrial permeability transition pore (mPTP) activity (By similarity). Plays a role in mitochondrial uncoupling by acting as a proton transporter: proton transport uncouples the proton flows via the electron transport chain and ATP synthase to reduce the efficiency of ATP production and cause mitochondrial thermogenesis (By similarity). Proton transporter activity is inhibited by ADP:ATP antiporter activity, suggesting that SLC25A5/ANT2 acts as a master regulator of mitochondrial energy output by maintaining a delicate balance between ATP production (ADP:ATP antiporter activity) and thermogenesis (proton transporter activity) (By similarity). Proton transporter activity requires free fatty acids as cofactor, but does not transport it (By similarity). Probably mediates mitochondrial uncoupling in tissues that do not express UCP1 (By similarity). Also plays a key role in mPTP opening, a non-specific pore that enables free passage of the mitochondrial membranes to solutes of up to 1.5 kDa, and which contributes to cell death. It is however unclear if SLC25A5/ANT2 constitutes a pore-forming component of mPTP or regulates it (By similarity). Acts as a regulator of mitophagy independently of ADP:ATP antiporter activity: promotes mitophagy via interaction with TIMM44, leading to inhibit the presequence translocase TIMM23, thereby promoting stabilization of PINK1 (By similarity). As part of the mitotic spindle-associated MMXD complex it may play a role in chromosome segregation.
Synonyms: AAC2; ANT2; T2; 2F1; T3
Tractability: Antibody: its Gene Ontology location is reachable by antibodies, with high confidence; UniProt predicts a signal peptide or a membrane-spanning region. PROTAC: ubiquitination databases record sites on it; its protein half-life has been measured; a small molecule that binds it is known.
Target class: Electrochemical transporter; Transporter; SLC25 family of mitochondrial transporters; SLC superfamily of solute carriers
Gene: Protein-coding gene on chromosome X (119,468,395 to 119,471,396, forward strand). Ensembl gene ENSG00000005022.
Subcellular location: Mitochondrion inner membrane; Membrane
Subcellular location (Human Protein Atlas): Mitochondria
Pathways (Reactome):
Disease: Vpr-mediated induction of apoptosis by mitochondrial outer membrane permeabilization
Metabolism of proteins: Mitochondrial protein degradation
Transport of small molecules: Transport of nucleosides and free purine and pyrimidine bases across the plasma membrane
Gene Ontology:
Molecular function: adenine nucleotide transmembrane transporter activity; protein binding; RNA binding; ubiquitin protein ligase binding; adenine transmembrane transporter activity; ATP:ADP antiporter activity; oxidative phosphorylation uncoupler activity; proton transmembrane transporter activity
Biological process: adenine nucleotide transport; negative regulation of mitochondrial outer membrane permeabilization involved in apoptotic signaling pathway; positive regulation of cell population proliferation; adaptive thermogenesis; B cell differentiation; erythrocyte differentiation; mitochondrial ADP transmembrane transport; mitochondrial ATP transmembrane transport; positive regulation of mitophagy; regulation of mitochondrial membrane permeability; adenine transport; proton transmembrane transport; transmembrane transport
Cellular component: membrane; mitochondrial nucleoid; mitochondrion; MMXD complex; nucleus; mitochondrial inner membrane; mitochondrial permeability transition pore complex; plasma membrane
Homologues: Orthologues: chimpanzee SLC25A5 (99% identical), guinea pig SLC25A5 (98% identical), rat Slc25a5 (98% identical), dog SLC25A5 (98% identical), mouse Slc25a5 (98% identical), pig SLC25A5 (98% identical), rat Slc25a5-ps11 (94% identical), zebrafish slc25a5 (92% identical), tropical clawed frog slc25a5 (91% identical). Paralogues in human: SLC25A6 (92% identical), SLC25A4 (89% identical), SLC25A31 (71% identical), SLC25A12 (30% identical), SLC25A13 (30% identical), SLC25A32 (29% identical), SLC25A43 (28% identical), SLC25A16 (27% identical), SLC25A36 (27% identical), SLC25A29 (26% identical), SLC25A1 (25% identical), SLC25A14 (25% identical), and 37 more.
Diseases named in the same sentence as SLC25A5 in open-access papers:
SLC25A5 is named in the same sentence as 79 diseases in open-access papers, as found by Europe PMC text mining. Sharing a sentence is not in itself a finding about the gene and the disease. The quoted sentences say what the papers report.
colon cancer (5 papers, 2022 to 2025). "Regarding the diagnostic efficacy of colon cancer, the AUCs of ROCs were 0.773 (CI: 0.736–0.809) for SLC25A5 and 0.771 for SLC25A24 (CI: 0.734–0.807)." (PMID 35288533, 2022). "A study showed that high expression of SLC25A5 indicated a longer survival time of patients with colon cancer." (PMID 41465541, 2025). "SLC25A5 mediated the MAPK signaling pathway to inhibit the malignant behavior in colon cancer cells." (PMID 38226966, 2024). "SLC25A5 inhibited the MAPK signaling pathway in colon cancer, reducing cell proliferation and increasing the expression of programmed cell death-related markers." (PMID 36601479, 2022). "Although high expression of most DEMs indicated a longer survival time of patients with colon cancer, only that of SLC25A5 (HR = 0.58, log-rank p < 0.01, 95% CI 0.38–0.90) and SLC25A24 (HR = 0.58, log-rank p < 0.01, 95% CI 0.39–0.85) met statistical significance." (PMID 35288533, 2022). "Furthermore, we initially validated our findings in clinical specimens and explored the function of the identified member (SLC25A5) in colon cancer-derived cell lines." (PMID 35288533, 2022). "To further evaluate the clinical value of SLC25A5 and SLC25A24 in colon cancer, we performed a series of bioinformatic investigations." (PMID 35288533, 2022). "To explore the function of SLC25A5 and SLC25A24 in colon cancer, we executed several cytological experiments in vitro." (PMID 35288533, 2022). "Low expression of SLC25A5 (p < 0.01) and SLC25A24 (p < 0.001) was observed in colon cancer compared to that in paired colonic epithelium." (PMID 35288533, 2022). "Although SLC25A5 and SLC25A24 displayed elevated expression compared to samples from The Genotype-Tissue Expression (GTEx), both were relatively lowly expressed in colon cancer based on samples from TCGA-COAD, which requires further experimental validation." (PMID 35288533, 2022). "A negative correlation between CD8 and SLC25A5 was determined in specimens from 106 patients with advanced colon cancer." (PMID 35288533, 2022). "Although it may seem paradoxical, our results suggested that SLC25, and in particular, SLC25A5 and SLC25A24, might be involved in the EGFR and ERK-MAPK signaling pathways in colon cancer and potentially serve as treatment targets." (PMID 35288533, 2022).
hepatocellular carcinoma (5 papers, 2014 to 2025). A malignant tumor that arises from hepatocytes. "Moreover, SLC25A5 is considered to be associated with lymph node metastasis of hepatocellular carcinoma." (PMID 34530829, 2021). "However, the expression of one member, SLC25A5, has been implicated in cancer cell metabolism, with expression shown to correlate with glycolytic metabolism in osteosarcoma and hepatocellular carcinoma cells." (PMID 25471892, 2014). "SLC25A5 enhances resistance to tyrosine kinase inhibitors in lung cancer and reverses resistance to immunotherapy in hepatocellular carcinoma." (PMID 40834150, 2025). "Overexpression of SLC25A5 could both strengthen resistance to tyrosine kinase inhibitors in lung cancer and reverse sorafenib resistance via the PI3K/AKT pathway in hepatocellular carcinoma." (PMID 35288533, 2022). "SLC25A5 specifically has been reported to be down-regulated with metastasis in hepatocellular carcinoma, with no information available for NBL." (PMID 30962767, 2019).
Intellectual disability (4 papers, 2018 to 2022). "Diseases associated with SLC25A5 protein include non-syndromic intellectual disability, Huntington’s and Parkinson’s diseases." (PMID 30537945, 2018). "SLC25A5 has been related to non‐syndromic intellectual disability." (PMID 32515122, 2020).
breast carcinoma (3 papers, 2022 to 2025). "The results showed that DYNLT1, IMMT, RAB2A, and SLC25A5 were unfavorable factors for breast cancer prognosis in the lipid metabolic pathway." (PMID 35919504, 2022). "SSBP1, TXNRD1, SLC25A5, DDOST, SEH1L, and MCM2 had a significant effect in at least 50% of breast cancer cell lines in the CRISPR-Cas9 and/or RNAi screening data." (PMID 37445737, 2023).
cervical cancer (3 papers, 2021 to 2023). A primary or metastatic malignant neoplasm involving the cervix. "Studies have shown that high expression of SLC25A5 in cervical cancer could be an independent prognostic factor." (PMID 35840882, 2022). "SLC25A5 and ENO1, which we found in our common core, were recently identified among six hub genes prognostic for cervical cancer." (PMID 36996232, 2023).
colorectal cancer (3 papers, 2022 to 2026). A primary or metastatic malignant neoplasm that affects the colon or rectum. "SLC25A5 has been demonstrated to attenuate cell proliferation and promote programmed cell death-related genes expression, and be positively correlated with the OS of colorectal cancer." (PMID 35783272, 2022). "Using Random Survival Forest (RSF) analysis with importance scoring, we identified seven key prognostic genes (CD24, SLC25A5, HSPB1, CD9, SPIMK1, LGALS4, and CEACAM5), which were subsequently designated as the Colorectal cancer Survival Signature (CSS)." (PMID 40777020, 2025).
COVID-19 (3 papers, 2021 to 2023). A disease caused by infection with severe acute respiratory syndrome coronavirus 2. "Through unbiased KEGG pathway analysis of DEGs between Fga−/− and WT plasma-stimulated microglia, we identified the 12 top pathways induced by fibrinogen, including ROS (for example, Hmox1, Cox7a2, Slc25a5), COVID-19 (for example, Ccl12, Rps8, Rpl35) and AD (for example, Atp5e, Psmd2, Tubb5)." (PMID 37291385, 2023).
Obesity (3 papers, 2018 to 2024). Accumulation of substantial excess body fat. "Then, we selected 5 variants in genes previously reported to be associated with obesity, adipogenesis or linked to obesity-associated traits by genome-wide association studies (SLC25A5, AIM2, SNX16, CAMKK2 and PDE11A) for further analysis to identify candidate MOVs." (PMID 38469147, 2024).
Alzheimer disease (2 papers, 2022 to 2025). A progressive, neurodegenerative disease characterized by loss of function and death of nerve cells in several areas of the brain leading to loss of cognitive function such as memory and language. "Our KEGG pathway analysis indicated that PPIF (Hyper/Up) physically interacts with SLC25A5 (STRING-db PPI) and is implicated in the cGMP-PKG signaling pathway and Alzheimer’s disease pathway." (PMID 40217422, 2025). "Among the top-ranked proteins in the PMbrown network, Ndufs4 and Slc25a5 are involved in Alzheimer’s disease pathway, showing that they play an important role in neurodegenerative diseases resulting from sleep disorders." (PMID 35432311, 2022).
anemia (2 papers, 2016 to 2022). A reduction in the number of red blood cells, the amount of hemoglobin, and/or the volume of packed red blood cells. "Depletion of SLC25A5 can cause mitochondrial dysfunction and induce oxidative stress, leading to erythrocyte anemia and B-cell depletion." (PMID 35840882, 2022). "SLC25A5 gene knockout mice showed a pale phenotype and postnatal growth was severely retarded with macrocytic anemia because of maturation arrest of the erythrocyte precursor." (PMID 28006025, 2016).
Anxiety (2 papers, 2013 to 2017). Intense feelings of nervousness, tension, or panic often arise in response to interpersonal stresses. "SLC25A5 encodes a mitochondrial protein associated with anxiety in mice." (PMID 29096718, 2017). "The mRNA levels of the genes coding for prohibitin 2 and SLC25A5 were also significantly increased (2.5-fold) in fish that developed anxiety and related phenotypes following chronic stress exposures." (PMID 23691016, 2013).
cervical squamous cell carcinoma (2 papers, 2022). A squamous cell carcinoma arising from the cervical epithelium. "Some genes of SLC25 were associated with poor prognosis of patients in cervical squamous cell carcinoma and endocervical adenocarcinoma, including SLC25A4, SLC25A5, SLC25A8, SLC25A14, SLC25A12, SLC25A23, and SLC25A41." (PMID 36254139, 2022). "Notably, for histological type, CAMK2A, CYBB, IL1A, IL1B, and SLC25A5 were found to be upregulated in patients with cervical squamous cell carcinoma compared with those having cervical adenosquamous carcinoma (P < 0.05)." (PMID 36253777, 2022).
depression (2 papers, 2023 to 2024). "Additionally, there exist a multitude of significant genes that vary between sexes and are linked to depression, like ORM1, ORM2, RNF32, SLC25A5, Thbs1, and Cadps2 etc., manifesting sex-specific impacts on depression risk." (PMID 38903903, 2024). "Our results also showed that the expression level of SLC25A5 in the blood of depression patients was low, suggesting that SLC25A5 may be related to negative mood." (PMID 37547246, 2023).
melanoma (2 papers, 2025 to 2026). A malignant, usually aggressive tumor composed of atypical, neoplastic melanocytes. "Validation using melanoma data from TIDE revealed that key CSS-associated molecules (CD24, HSPB1, SLC25A5) profoundly influenced immunotherapy outcomes." (PMID 40777020, 2025). "Moreover, melanoma patients receiving immune checkpoint blockade (ICB) therapy with high expression of CD24, HSPB1, and SLC25A5 also had a poor prognosis." (PMID 40777020, 2025).
Parkinson disease (2 papers, 2013 to 2018). A progressive degenerative disorder of the central nervous system characterized by loss of dopamine producing neurons in the substantia nigra and the presence of Lewy bodies in the substantia nigra and locus coeruleus. "Another protein that was dysregulated in zebrafish brain was SLC25A5 (solute carrier family 25 member 5), which has been linked to autism and Parkinson’s disease." (PMID 23691016, 2013).
breast tumors (1 paper, 2007). "MCF-7 cells, unlike ZR75-1 and breast tumors, had a high glycolytic rate, which correlated with a high expression of SLC25A5/ANT2 (Complex V, electron transport chain)." (PMID 17883861, 2007).
cardiomyopathies (1 paper, 2025). "Remarkably, in both cardiomyopathies, Ca2+ storage in the mitochondrion was diminished by downregulation of one of the involved genes (Vdac1 in CCC and Slc25a5 in IHF mice)." (PMID 41296444, 2025).
clear cell renal cell carcinoma (1 paper, 2022). "SLC25A5 was identified as a biomarker in clear cell renal cell carcinoma involving competitive endogenous RNA." (PMID 35995782, 2022).
colon adenocarcinoma (1 paper, 2022). "Among surgical resection specimens of colon adenocarcinoma and paired colonic epithelium, 72 and 78 of 79 cases with progressive disease were successfully stained and evaluated for SLC25A5 and SLC25A24, while 87 and 103 of 106 cases with advanced disease finished the same work." (PMID 35288533, 2022).
colorectal adenocarcinoma (1 paper, 2025). The most common type of colorectal carcinoma. "Potential diagnostic transcripts may include ADH1C, GGT5, NQO2, and SLC25A5 in colorectal adenocarcinoma." (PMID 41465541, 2025).
end-stage renal disease (1 paper, 2023). "SCL25A3 was found to be differentially expressed in sclerosis-prone ROP-Os/+ and sclerosis resistant C57-Os/+ mouse kidneys, and both SLC25A5 and SLCA25A6 genes are reported to be modulated in type 2 diabetic patients with end-stage renal disease." (PMID 36769128, 2023).
esophageal carcinoma (1 paper, 2023). A primary or metastatic malignant neoplasm involving the esophagus. "Moreover, some CRGs, including PIH1D2, SLC23A2, SLC25A5, ATP7A, PDHX and COX7B, were reported to be tightly linked with the grading and immune infiltration of esophageal carcinoma." (PMID 37380924, 2023).
head and neck squamous cell carcinoma (1 paper, 2022). A squamous cell carcinoma that arises from any of the following anatomic sites: lip and oral cavity, nasal cavity, paranasal sinuses, pharynx, larynx, and salivary glands. "In head and neck squamous cell carcinoma, SLC25A9, SLC25A23, SLC25A4, and SLC25A5 all showed decreased expression." (PMID 36254139, 2022).
Huntington disease (1 paper, 2024). Huntington disease (HD) is a rare neurodegenerative disorder of the central nervous system characterized by unwanted choreatic movements, behavioral and psychiatric disturbances and dementia. "SLC25A5 demonstrated significant enrichment in huntington's disease within the high expression group, while its predominant association with the chemokine signaling pathway was evident in the low expression group (Fig. 6A1, A2)." (PMID 38965390, 2024).
Hyperoxaluria (1 paper, 2022). Increased excretion of oxalates in the urine. "Also, SLC25A5 has a role in the calcium homeostasis but its relation to hyperoxaluria needs to be investigated." (PMID 36619171, 2022).
hypospadias (1 paper, 2020). Hypospadias is the displacement of the urethral meatus on the ventrum of the penis. "Compound rare damaging mutants of AR gene with HSD3B1 and SLC25A5 genes were identified in the different severe hypospadias." (PMID 32515122, 2020). "And the deletion encompassing SLC25A43, LOC100303728, SLC25A5, CXorf56, UBE2A, NKRF, and SEPT6, is associated with hypospadias." (PMID 32515122, 2020). "The data herein provided direct evidence that SLC25A5 may contribute the genetic etiology of hypospadias." (PMID 32515122, 2020).
invasive breast carcinoma (1 paper, 2023). A carcinoma that infiltrates the breast parenchyma. "DYNLT1, IMMT, RAB2A, and SLC25A5 are independent prognostic factors for invasive breast carcinoma and confer a poor prognosis 2)." (PMID 37179822, 2023).
leukemia (1 paper, 2021). A malignant (clonal) hematologic disorder, involving hematopoietic stem cells and characterized by the presence of primitive or atypical myeloid or lymphoid cells in the bone marrow and the blood. "In stark contrast, the expression profiles of the three main ANT isoforms were entirely distinct between PBMC and leukemia mitochondria, highlighted by reduced ANT1 (SLC25A4) and increased ANT2 (SLC25A5) and ANT3 (SLC25A6) in leukemia." (PMID 34132194, 2021).
memory impairment (1 paper, 2020). "Slc25a5 and Nipsnap1 play prominent roles in signal transduction and postsynaptic density function regulation, therefore, the abnormal expression of these genes can result in memory impairment." (PMID 33221746, 2020).
mesothelioma (1 paper, 2024). A usually malignant and aggressive neoplasm of the mesothelium which is often associated with exposure to asbestos. "Interestingly, a recent study has identified a deletion mutant of Slc25a5 associated with familial predisposition to mesothelioma." (PMID 38694815, 2024).
metastatic cancer (1 paper, 2024). A carcinoma which has spread from the original site of growth to another anatomic site. "Analysis of EVs of TKI-resistant cancer cells as well as plasma of patients with TKI-resistant metastatic cancer reveal an enrichment in SLC1A5 and SLC25A5 solute carrier transporters and ALDHA1." (PMID 39431017, 2024).
myocardial hypertrophy (1 paper, 2022). "In our study, we found that SLC25A5 is positivelycorrelated with CSRP3, indicating that SLC25A5 might alsoparticipate in the process of myocardial hypertrophy." (PMID 39076905, 2022).